BRSK2 (BR serine/threonine kinase 2)
Diseases named in the same sentence as BRSK2 in open-access papers:
BRSK2 is named in the same sentence as 50 diseases in open-access papers, as found by Europe PMC text mining. Sharing a sentence is not in itself a finding about the gene and the disease. The quoted sentences say what the papers report.
autism (5 papers, 2019 to 2026). Persistent deficits in social interaction and communication and interaction as well as a markedly restricted repertoire of activity and interest as well as repetitive patterns of behavior. "Previous studies have reported that BRSK2 interacts with NDD-associated genes such as autism and developmental delay (DD) and/or intellectual disability (ID)." (PMID 37671287, 2023). "The relationship between BRSK2 and autism has only been clarified in recent years, and many aspects still need further research and exploration." (PMID 41596506, 2026). "Also, BRSK2 interacts with PTEN, which is associated with various developmental disorders (e.g., autism)." (PMID 37671287, 2023). "Although phenotyping and genotyping assessments of patients implicate damaging variants in BRSK2 as contributing to autism, sufficient evidence is lacking to further verify the correlation between BRSK2 and ASD and its underlying molecular mechanism based on animal models." (PMID 35754711, 2022). "Among highly expressed genes in Autism and other disorders, I also found AFF2 and BRSK2, both with score 1 in SFARI and reportedly critical for neurodevelopment." (PMID 34834471, 2021).
Cognitive impairment (4 papers, 2019 to 2023). Abnormal cognition is characterized by deficits in thinking, reasoning, or remembering. "In human studies, a BRSK2 polymorphism (rs1881509) has been associated with heroin dependence, and functional variants of BRSK2 have been associated with autism spectrum disorder, cognitive impairment, intellectual disability, and speech delays." (PMID 34799556, 2021). "All four individuals in SPARK, ASC and the SSC with de novo functional variants in BRSK2 are males with cognitive impairment and severe speech delay." (PMID 31452935, 2019). "Seven differentially expressed autoantibodies were recognised as cognitive impairment-related, including HSPD1, CDK19, TKT, BRSK2, NRAS, LMNA, and CAMK2A." (PMID 38107644, 2023).
diabetes (4 papers, 2020 to 2024). "Third, acute induction of BRSK2 expression in mature β cells caused severe hyperinsulinemia and mild hyperglycemia within a week, while chronic BRSK2 overexpression triggered frank diabetes characterized by insulin resistance and GSIS disability." (PMID 37188647, 2023). "However, islet adaptation would entail hyperinsulinemia, which promotes insulin resistance and β-cell exhaustion and inevitably leads to diabetes, as that occurs in BRSK2-overexpressing mice." (PMID 37188647, 2023). "Therefore, BRSK2 is more likely a metabolic response molecule that executes LKB1 function during diabetes onset." (PMID 37188647, 2023). "We have provided definitive evidence that gain-of-function BRSK2 in β cells directly initiates β-cell hypersecretion, insulin resistance, and GSIS disability in mice, while loss-of-function BRSK2 in adulthood restrains diet-induced obesity and maintains GSIS function to prevent diabetes insult." (PMID 37188647, 2023). "However, whether BRSK2 is associated with human type 2 diabetes mellitus (T2DM) has not been determined." (PMID 37188647, 2023). "Next, we examined the BRSK2 protein expression in human pancreas slices from T2DM patients and non-diabetes donors." (PMID 37188647, 2023). "The study did not include BRSK2 as a target because it focused on the biological functions of LKB1 in knockout mice rather than the pathological effects on disease development, e.g. diet-induced obesity and diabetes." (PMID 37188647, 2023).
Anxiety (3 papers, 2021 to 2023). Intense feelings of nervousness, tension, or panic often arise in response to interpersonal stresses. "Other genes previously linked to mood, anxiety, or trauma-related disorders included protein zeta-1 (FEZ1), ADCYAP1, BRSK2, catenin alpha 3 (CTNNA3), and par-3 family cell polarity regulator (PARD3)." (PMID 34799556, 2021).
Intellectual disability (3 papers, 2021 to 2023). "Indeed, the X-linked gene AFF2 has been found in patients with fragile X E (FRAXE) intellectual disability, while the gene encoding the serine/threonine-protein kinase BRSK2 was recently detected in individuals with developmental and intellectual disability." (PMID 34834471, 2021).
developmental delay (2 papers, 2022 to 2023). "A study reported nine patients with rare, heterozygous variants in BRSK2 from cohorts including 3,429 probands with developmental delay/intellectual disability (DD/ID)." (PMID 35754711, 2022). "These discoveries are analogous to patients with BRSK2 variants in that 84.6% of reported cases (11/13) experienced motor developmental delays at an early age and exhibited motor function impairments thereafter." (PMID 35754711, 2022). "Meanwhile, BRSK2-mutant zebrafish exhibited ASD-like features (e.g., developmental delay, social impairment)." (PMID 37671287, 2023).
heroin dependence (2 papers, 2016 to 2021). Physical and psychological dependence on the drug heroin. "Analysis using the diagnostic criteria of heroin dependence yielded suggestive evidence for association between variants in the genes CCDC42 (coiled coil domain 42; p = 2.8x10-7) and BRSK2 (BR serine/threonine 2; p = 4.110−6)." (PMID 27936112, 2016).
lung carcinoma (2 papers, 2017 to 2021). "Another novel autoantigen was discovered in 2005 by Sabater’s group, who diagnosed serum BR serine/threonine kinase 2 (BRK2) antibodies in a patient with a “limbic syndrome” in conjunction with lung cancer crucial for neuronal transmission and development." (PMID 33026492, 2021).
neuropathy (2 papers, 2021 to 2024). A disorder affecting the nervous system that manifests with pain, tingling, numbness, and/or muscle weakness. "Moreover an EWAS found that participants with type 1 diabetes and neuropathy showed decreased methylation at four CpG sites in the BRSK2 gene compared to participants with type 1 diabetes without neuropathy." (PMID 34799556, 2021).
pancreatic carcinoma (2 papers, 2015 to 2017). "Knockdown of endogenous BRSK2 expression enhances ER stress-mediated apoptosis in human pancreatic carcinoma and HeLa cells." (PMID 26540294, 2015). "Along with our previous BRSK2 data, this implied that BRSK2 upregulation in pancreatic cancer might enhance the activity of Akt via mTORC1 inhibition." (PMID 28591720, 2017). "Consistent with the nutrient dependent upregulation of AMPK family protein, BRSK2 expression level is inversely related to microvessel density (MVD) and microvessel coverage fraction in pancreatic cancer (r= -0.349, p<0.001; r=-0.255, p<0.008)." (PMID 28591720, 2017).
breast carcinoma (1 paper, 2021). "For example, those interested in studying BRSK2 activity in breast cancer may be inclined to use MCF7 cells due to higher levels seen by qPCR and immunoblot." (PMID 34084284, 2021). "In all breast cancer combined, high expression of LKB1, AMPK, LYK5, MARK1, MARK2, NUAK2, PAK1 (both probe sets), SIK1, SIK2, BRSK1, BRSK2, SNRK, and QSK was positively correlated with improved survival compared to low expression of these genes." (PMID 34084284, 2021).
cyst (1 paper, 2022). A sac-like closed membranous structure that may be empty or contain fluid or amorphous material. "Therefore, a search process on PubMed was conducted, where BRSK2 has searched along with different terminologies such as ADPKD, ARPKD, PKD, Cyst, and kidney." (PMID 36422197, 2022).
depression (1 paper, 2021). "However, the associations between decreased BRSK2 CpG3 methylation at 3-months post-rape and increased PTSD scores at 3-months post-rape were the only ones that remained significant after childhood trauma, alcohol consumption, depression, and lifetime trauma were added as covariates to the models." (PMID 34799556, 2021). "However, the relationships between BRSK2 CpG3, CpG4, and CpG5 methylation levels and PTSD scores at 3-and 6-months post-rape were no longer significant when childhood trauma, alcohol consumption, depression, and lifetime trauma were added to the models as covariates." (PMID 34799556, 2021).
Glucose intolerance (1 paper, 2023). Glucose intolerance (GI) can be defined as dysglycemia that comprises both prediabetes and diabetes. "Mice with pancreas-specific Brsk2 deletion exhibit oral glucose intolerance but maintain normal glucose excursion after intraperitoneal (i.p.) glucose injection due to loss of the gut hormone GLP-1." (PMID 37188647, 2023).
Hyperglycemia (1 paper, 2023). An increased concentration of glucose in the blood. "Conversely, gain-of-function BRSK2 in mature β cells reversibly triggers hyperglycemia due to β-cell hypersecretion-coupled insulin resistance." (PMID 37188647, 2023). "An increase in BRSK2 occurs prior to insulin resistance and hyperglycemia in HFD-fed mice, indicating an attempt to remodel β-cell function, islet mass, and architecture as part of a response to mild metabolic stress." (PMID 37188647, 2023). "The hyperglycemia in TG mice did not result from absolute insufficiency of serum insulin levels, since circulating insulin, proinsulin, and C-peptide levels were significantly increased in TG mice after Dox administration, indicating that BRSK2 might trigger β-cell hypersecretion." (PMID 37188647, 2023).
Hyperinsulinemia (1 paper, 2023). An increased concentration of insulin in the blood. "Taken together, BRSK2 locus variants potentially play roles in regulating glucose metabolism in humans to be associated with both hyperinsulinemia and insulin resistance." (PMID 37188647, 2023). "The possible associations between BRSK2 and the initiation of hyperinsulinemia and insulin resistance were assessed by determining the mRNA and protein levels of BRSK2 in islets from mice fed a high-fat diet (HFD) for different durations." (PMID 37188647, 2023). "We used inducible gain-of-function and loss-of-function variants of β-cell Brsk2 to show that the amount of BRSK2 in mature β cells was positively associated with hyperinsulinemia, insulin resistance, and the onset of T2DM." (PMID 37188647, 2023). "Here, we report that BRSK2 genetic variants are closely related to worsening glucose metabolism due to hyperinsulinemia and insulin resistance in the Chinese population." (PMID 37188647, 2023). "BRSK2 variant carriers may exhibit congenital hyperinsulinism due to β-cell hypersecretion, which causes a vicious cycle between hyperinsulinemia and insulin resistance, akin to the most recognized genetic variants of ABCC8 and KCNJ11 in T2DM." (PMID 37188647, 2023). "The hyperinsulinemia-coupled insulin resistance phenotypes in BRSK2 variant carriers recalled the hotly debated viewpoint that β cells may initiate the development and progression of T2DM via crosstalk with insulin-sensitive tissues, such as the liver, adipose tissue, and skeletal muscle." (PMID 37188647, 2023). "Taken together, our data demonstrated that BRSK2 is both required and sufficient for hyperinsulinemia, likely in part via enhancing insulin secretion." (PMID 37188647, 2023). "Nevertheless, the increased BRSK2 protein level in human T2DM islets suggested that gain-of-function mutants of BRSK2 contribute to hyperinsulinemia-coupled insulin resistance." (PMID 37188647, 2023). "Thus, our data demonstrated that BRSK2 deletion in mature β cells protected HFD-fed mice against hyperinsulinemia and insulin resistance." (PMID 37188647, 2023). "Hence, our data demonstrated that BRSK2 overexpression in β cells drives hyperinsulinemia and peripheral insulin resistance." (PMID 37188647, 2023). "However, immunostaining results from TG mice revealed a negative association between BRSK2 expression levels and the remaining insulin levels, indicating that single β-cell hypersecretion contributes to hyperinsulinemia-induced insulin resistance." (PMID 37188647, 2023). "First, BRSK2 protein level was also enhanced in mouse islets within one month of HFD feeding, accompanied by hyperinsulinemia and overweight but euglycemia." (PMID 37188647, 2023).
Hypoinsulinemia (1 paper, 2023). A decreased concentration of insulin in the blood. "Mice with whole-body knockout of Brsk2 remain healthy and fertile but exhibit growth retardation and hypoinsulinemia." (PMID 37188647, 2023).
IgA nephropathy (1 paper, 2026). "Transcriptomic-wide MR identified candidate genes across GN subtypes: RECQL, BRSK2, and MGP in acute GN; AFM, CFHR5, and EPHB2 in chronic GN; IL6R, MBL2, and PRSS3 in IgA nephropathy; and TIMP4, HCK, and PEAR1 in membranous nephropathy." (PMID 41990104, 2026).
Insulin resistance (1 paper, 2023). Increased resistance towards insulin, that is, diminished effectiveness of insulin in reducing blood glucose levels. "These shrunk adipose tissues in BRSK2-overexpressing mice might be attributed to the acute insulin resistance caused by massive insulin secretion, consistent with the phenomenon caused by the insulin receptor antagonist S961." (PMID 37188647, 2023). "In the present study, we demonstrated that BRSK2 links β-cell hypersecretion to diet-induced obesity, insulin resistance and T2DM." (PMID 37188647, 2023). "The enhanced basal insulin secretion drives insulin resistance and β-cell exhaustion and thus the onset of T2DM in mice fed an HFD or with gain-of-function BRSK2 in β cells." (PMID 37188647, 2023). "In conclusion, human genetic data coupled with in vivo and in vitro experiments clearly indicate a critical role of BRSK2 in regulating GSIS function, subsequent systematic insulin resistance, and T2DM through crosstalk between β cells and insulin target tissues." (PMID 37188647, 2023).
Obesity (1 paper, 2023). Accumulation of substantial excess body fat. "BRSK2 also plays key roles in sensing nutrient signals and may lead to obesity and metabolic disorders." (PMID 37188647, 2023).
pancreatic ductal adenocarcinoma (1 paper, 2023). An infiltrating adenocarcinoma that arises from the epithelial cells of the pancreas. "BRSK2, which belongs to the serine/threonine-protein kinase of the AMPK family, was recognized to be a risk factor for pancreatic ductal adenocarcinoma (PDAC)." (PMID 36681855, 2023).
cancer (8 papers, 2018 to 2025). A tumor composed of atypical neoplastic, often pleomorphic cells that invade other tissues. "Other less understudied commonly upregulated kinases that were frequently found to be significant in survival (≥5 cancers) included the BRSK2, ERN2, PNCK, and STK31 kinases." (PMID 33801837, 2021). "For instance, a hypomethylation was observed in CpG sites associated with cancer-related genes: leucine-rich repeat-containing 26 (LRRC26), homeobox B9 (HOXB9), and BR serine/threonine kinase 2 (BRSK2) only in boys, which correlated with an increase in As levels." (PMID 30873799, 2018). "Among these, the genes PKMYT1, PNCK, BRSK2, ERN2, and STK31 were significant in survival in five or more cancers." (PMID 33801837, 2021). "The most investigated genes were those implicated in neuroendocrine stress responses; dopamine, norepinephrine, and serotonin signalling; apoptosis; insulin secretion; neuroplasticity; reproduction; foetal growth; and cancer (e.g. MAOA, BRSK2, ADCYAP1, BDNF, DRD2, IGF2, H19)." (PMID 41070359, 2025). "Interestingly, searching BRSK2 against mTOR yielded several hits describing the involvement of the BRSK2 protein and TSC2 in the regulation of mTOR signaling in different contexts, including cancer cell survival and development." (PMID 36422197, 2022).
tumor (7 papers, 2012 to 2025). "BRSK2 downregulation by the MEK mutant gene results in dysregulated cell proliferation and tumor growth, as BRSK2 regulates the G1/S transition." (PMID 41009348, 2025). "Both IHC and western blotting data showed that BRSK2 levels in the tumor tissues are positively correlated with pAkt substrate intensity (r=0.280, p=0.030; r=0.832, p=0.001)." (PMID 28591720, 2017). "An abridged list contains 23 hypermethylated genes and 4 hypomethylated genes (CACNA2D4;LRTM2, ESPNL, SECTM1, PCDH8) for AA tumor samples; whereas, 29 hypermethylated genes and 1 hypomethylated gene (BRSK2) are listed for the CA tumor samples." (PMID 27111221, 2016). "The importance of FBF1 and BRSK2 in tumor initiation or progression has yet to be shown, but it is known that these genes are required for the establishment of epithelial cell polarity." (PMID 27014907, 2016). "To test whether BRSK2 expression was related to the nutrient supply of PDAC, we have compared the expression of BRSK2 in tumor tissues with microvasculature parameters which reflect the energy supply in tumors." (PMID 28591720, 2017). "Moreover, our Immunohistochemical staining assay with tumor samples further revealed a close correlation between BRSK2 protein level and TSC2 Ser1387 phosphorylation level." (PMID 28591720, 2017). "BRSK2 was originally identified as a gene expressed specifically in the brain, but recent studies showed that BRSK2 is also expressed in some tumor cell lines, such as HeLa and Panc-1, which implies that BRSK2 might have complex and important biological functions related to tumor cell growth." (PMID 23029325, 2012). "However, BRSK2 mRNA levels were not altered by CREB knockdown with cisplatin treatment, except in H1299 tumor spheroids, suggesting that BRSK2 is unlikely to be a direct transcriptional target of CREB." (PMID 40860181, 2025).
neurodevelopmental disorder (2 papers, 2025 to 2026). A behavioral and cognitive disorder with onset during the developmental period that involves impaired or aberrant development of intellectual, motor, or social functions. "Addressing these constraints in future research will be essential for a more comprehensive understanding of BRSK2′s role in neurodevelopmental disorders." (PMID 41596506, 2026). "Increasing evidence suggests that BRSK2 is a high-risk ASD gene, with mutations leading to a variety of neurodevelopmental disorder phenotypes including language delay, motor delay and ASD." (PMID 41596506, 2026). "These include 10 that we classified as high interest VUS (ACMG total score = 0.60–0.75), such as SOX5 (delayed speech and language development) and BRSK2 (neurodevelopmental disorders)." (PMID 40325133, 2025). "Given the strong association of BRSK2 with ASD, this study addresses a significant knowledge gap by linking a key neurodevelopmental gene to specific sensory phenotype, potentially revealing mechanisms underlying sensory abnormalities in neurodevelopmental disorders." (PMID 41596506, 2026).
neurological disorders (2 papers, 2022 to 2023). "BRSK2 deficiency has been linked to numerous neurodevelopmental and neurological disorders, including autism spectrum disorder (ASD), developmental delays, and/or intellectual disability." (PMID 38003696, 2023). "Therefore, these cases indicate that BRSK2 is relatively intolerant to protein-altering variation and plays a role in neurological diseases including ASD." (PMID 35754711, 2022). "Although the function of the BRSK2 gene is still under investigation, earlier research has indicated its involvement in neuronal development and plasticity, cell polarity and migration, the formation of presynaptic vesicles, axonal development, neuronal polarization, and neurological disorders." (PMID 38003696, 2023).
BRSK2 also shares sentences with these, for which no sentence is quoted: autism spectrum disorder (3 papers); cardiovascular disease (2); Alzheimer disease (1); anxiety disorder (1); autoimmune thyroiditis (1); dental caries (1); diffuse large B-cell lymphoma (1); gout (1); infection (1); intestinal disease (1); liver cancer (1); liver cirrhosis (1); melanoma (1); membranous nephropathy (1); osteosarcoma (1); prostate carcinoma (1); prostate tumors (1); sarcoidosis (1); speech delays (1); testicular germ cell tumor (1); thyroid carcinoma (1); type 1 diabetes (1); type 2 diabetes (1); uterine carcinosarcoma (1); viral infection (1).